CGAS (cyclic GMP-AMP synthase)
Diseases named in the same sentence as CGAS in open-access papers (continued):
Sharing a sentence is not in itself a finding about the gene and the disease.
tauopathy (12 papers, 2021 to 2025). Neurodegenerative disorders involving deposition of abnormal tau protein isoforms (tau proteins) in neurons and glial cells in the brain. "Quantification of densities of PSD-95, a marker of excitatory postsynaptic terminals, in the striatum radiatum revealed that cGAS ablation rescued tauopathy-induced PSD-95 loss in CA1 pyramidal neurons." (PMID 37095396, 2023). "This was directly evidenced with the ICP27 protein of HSV1, which triggered cGAS-STING antiviral activity as well as tauopathy in neurons and microglia of AD patients." (PMID 40305226, 2025). "A recent study found that cGAS-STING is activated in the P301S tauopathy mouse model and human AD brains with high tau pathology levels." (PMID 39272998, 2024). "The pharmacological inhibition of cGAS by the brain penetrant molecule TDI-8246 in mice with tauopathy restored synaptic integrity, plasticity, and memory." (PMID 39272998, 2024). "Two recent independent studies revealed the involvement of the cGAS-STING pathway in 5xFAD amyloidosis and P301S tauopathy mouse models, with a focus on cGAS manipulation." (PMID 39218977, 2024). "Here, we investigated cGAS–STING–IFN activation in microglia in mice with tauopathy and in brain samples from individuals with AD." (PMID 37095396, 2023). "In a recent study, we found that cGAS-STING is activated in the P301S tauopathy mouse model and human AD brains harboring high levels of tau pathology." (PMID 37941028, 2023). "Work in transgenic tauopathy mouse models has shown that microglia drive tau pathology and tau-mediated neurodegeneration and that tau pathology drives an activated microglial response through cyclic GMP-AMP synthase and interferon signaling." (PMID 38438877, 2024). "Interestingly, the evidence supports that elevated mtDNA in the cytosol serves as the major trigger of cGAS-STING in TBI, consistent with findings in tauopathy and TDP43-associated ALS/FTD models." (PMID 37941028, 2023). "Thus, the cGAS–STING pathway is activated in P301S transgenic mice with tauopathy and in AD brain samples." (PMID 37095396, 2023). "We asked whether inhibiting cGAS ameliorates tauopathy-induced defects." (PMID 37095396, 2023). "Tau-induced activation of cGAS–STING pathway might underlie a more general inflammatory response that is independent of progression patterns of tauopathy in the central nervous system." (PMID 34782623, 2021). "This disruption produces an IFN response independent from cGAS-STING activation, indicating a separate proinflammatory proteinopathy from the intracellular tauopathies discussed." (PMID 40305226, 2025). "Our analyses of two datasets revealed that tau induced a strong cGAS activation and IFN-I response in mice with tauopathy." (PMID 37095396, 2023). "Evidence from mouse tauopathy models and AD neural spheroids has shown that lamivudine can effectively suppress retrotransposon activation, attenuate neuroinflammation (especially TLR and cGAS activation), and preserve neuronal viability." (PMID 40165251, 2025). "Sequencing results from hippocampal tissue in a tau-induced disease model revealed elevated levels of cGAS and STING, while genetic ablation of cGAS in mice with tauopathy alleviated the activation of IFN-I response in microglia, without altering the pathological tau load in the brain." (PMID 40038765, 2025). "Notably, TDI-6570, one of the most potent inhibitors for mouse cGAS, possesses good brain permeability and has been used to determine the effects of cGAS inhibition on cGAS-STING pathway in a mouse model of tauopathy." (PMID 37941028, 2023). "Additionally, pharmacological inhibition using TDI-6570, a non-toxic, brain-penetrant cGAS inhibitor, enhanced the neuronal MEF2C transcriptional network in the tauopathy mouse model, restoring synaptic integrity, plasticity, and memory." (PMID 40038765, 2025).
Cerebral ischemia (11 papers, 2020 to 2025). Restriction of arterial blood supply to the brain associated with insufficient oxygenation to support the metabolic requirements of the tissue. "The cGAS/STING/IRF3 pathway mediates neuroinflammation during cerebral ischemia, where hyperactivation promotes excessive production of proinflammatory cytokines (e.g., TNF-α, IL-6) and chemokines, exacerbating cerebral damage." (PMID 41471264, 2025). "Here, we found that cerebral ischemia promoted the release of dsDNA into the cytosol, where it initiated inflammatory responses by activating the cGAS." (PMID 32239625, 2020). "This study for the first time extends the crucial role of cGAS from the field of antiviral infection, anti‐tumor immunity, and cellular senescence to brain ischemic diseases, highlighting new targets for immunotherapeutic applications." (PMID 32239625, 2020). "However, it has been established that excessive activation of the cGAS-STING pathway during cerebral ischemia leads to NCOA4 overexpression, resulting in iron accumulation in neuronal cells." (PMID 37915571, 2023). "Moreover, histone deacetylase 3 (HDAC3) activates the cGAS-STING pathway and the deletion of cGAS or HDAC3 in microglia attenuates cerebral ischemia/reperfusion-induced neuroinflammation and brain injury." (PMID 35456028, 2022). "Taken together, these data suggest that increased release of self‐derived dsDNA within the cytosol may trigger the activation of cGAS‐STING pathway during brain ischemia." (PMID 32239625, 2020). "However, whether pharmacologically antagonizing dsDNA‐sensing cGAS via A151 could govern pyroptosis and the overall neuroinflammation in the context of brain ischemia still remains poorly defined." (PMID 32239625, 2020). "Of note, elevated cGAS and STING are predominantly localized in the microglia of the impaired cortex following CVST, and coincident cell localization has been reported in cerebral ischemia/reperfusion (I/R) and subarachnoid hemorrhage models." (PMID 35689216, 2022). "Rationale: It is known that neuroinflammation plays a critical and detrimental role in the development of cerebral ischemia/reperfusion (I/R), but the regulation of the cyclic GMP-AMP synthase (cGAS)-mediated innate immune response in I/R-induced neuroinflammation is largely unexplored." (PMID 32863951, 2020).
endothelial dysfunction (11 papers, 2021 to 2026). In vascular diseases, endothelial dysfunction is a systemic pathological state of the endothelium (the inner lining of blood vessels) and can be broadly defined as an imbalance between vasodilating and vasoconstricting substances produced by (or acting on) the endothelium. "Although activation of the cGAS-STING pathway has been shown to be involved in degeneration of the nervous system and cardiac dysfunction caused by aging, the role of the cGAS-STING pathway in aging-related endothelial dysfunction remains unknown." (PMID 36465181, 2022). "Further, cGAS/STING seem to play a key role in the increased endothelial dysfunction mediated by APOL1 risk variants and might contribute to explain the increased sepsis incidence and severity among patients of African ancestry." (PMID 35095882, 2021). "Previous studies have shown that activation of the cGAS-STING pathway plays a pivotal role in aging-related endothelial dysfunction." (PMID 39700692, 2025). "In summary, the cGAS-STING pathway integrates the effects of AS risk factors and orchestrates a series of cellular responses, including inflammatory reactions, endothelial dysfunction, lipid uptake in macrophages, changes in VSMCs, and oxidative stress." (PMID 40351606, 2025). "A recent study demonstrated that outer membrane vesicles (OMVs) of P. gingivalis can induce endothelial dysfunction via the Cyclic GMP-AMP synthase-stimulator of interferon genes–tank-binding kinase 1 (cGAS-STING-TBK1) signaling cascade." (PMID 39203574, 2024). "Activation of the cGAS-STINGpathway can lead to reduced eNOS activity and decreased NO production,contributing to endothelial dysfunction and impaired vasodilation." (PMID 39076568, 2024). "Our study demonstrated that activation of the cGAS-STING pathway played a vital role in aging-related endothelial dysfunction." (PMID 36465181, 2022). "Here, we examined the relationship between the cGAS-STING pathway and aging-associated endothelial dysfunction." (PMID 36465181, 2022). "The purpose of this study was to investigate the role of the cyclic GMP-AMP synthase (cGAS)-stimulator of interferon genes (STING) pathway in aging-related endothelial dysfunction." (PMID 36465181, 2022). "Age played a role in cGAS-STING induced endothelial dysfunction in cardiovascular diseases, however, its effect in respiratory diseases remains unknown." (PMID 37406004, 2023). "Moreover, the cGAS-STING pathway activation is critical for age-related endothelial dysfunction." (PMID 40351606, 2025). "Interestingly, an increase in p-IRF3 levels, the downstream target of cGAS and STING, was observed predominantly in the intima, which is consistent with our hypothesis that aging induces the endothelial dysfunction of blood vessels via the cGAS-STING pathway." (PMID 36465181, 2022). "This further leads to the engagement of cGAS-STING-IRF3 signaling to block angiogenesis, contributing to vascular complications induced by endothelial dysfunction." (PMID 38152400, 2023). "Cytosolic DNA is sensed by the NLRP3 inflammasome and by cGAS, an activator of STING, leading to endothelial dysfunction." (PMID 35095882, 2021).
head and neck squamous cell carcinoma (11 papers, 2021 to 2025). A squamous cell carcinoma that arises from any of the following anatomic sites: lip and oral cavity, nasal cavity, paranasal sinuses, pharynx, larynx, and salivary glands. "Other studies have shown that NET-related long intergenic non-protein coding RNA 426 (LINC00426) contributes to the innate immune cyclic GMP-AMP synthase (cGAS)-stimulator of interferon genes (STING) signaling pathway in head and neck squamous cell carcinoma." (PMID 36993957, 2023). "We found that the expression of cGAS in head and neck squamous cell carcinoma (HNSCC) cells was high among solid tumor cell lines, and that HNSCC patients with high levels of cGAS in The Cancer Genome Atlas (TCGA) cohorts had a poor outcome." (PMID 35563740, 2022). "In silico analysis using public databases suggested that high cGAS expression in head and neck squamous cell carcinoma (HNSCC) is indicative of a poor prognosis for HNSCC patients." (PMID 35563740, 2022). "This study investigates the role of the tumor cell–intrinsic cGAS–IFN-I pathway in immune surveillance using mouse models of oral squamous cell carcinoma, a major subtype of head and neck squamous cell carcinoma (HNSCC)." (PMID 40282455, 2025). "Similarly, Mn2+-enriched shikonin-loaded nanoparticles induce necroptosis in head and neck squamous cell carcinoma (HNSCC), disrupting mismatch repair to activate cGAS-STING-dependent IFN responses and enhance PD-1 blockade efficacy by promoting DC maturation and cytotoxic T cell infiltration." (PMID 41235238, 2025). "Moreover, in head and neck squamous cell carcinoma (HNSCC), therapeutic inhibition of MYC promoted intrinsic anti-tumor immune responses through the cGAS-STING signaling pathway, and CD8+ T-cell infiltration of HNSCC in vivo." (PMID 38390324, 2024). "Treatment of HPV-positive head and neck squamous cell carcinoma (HNSCC) cells with a combination of cisplatin and this new peptide synergistically increases cell mortality, although the intrinsic link between E7-induced mitophagy and the inhibition of cGAS-STING during chemotherapy remains unclear." (PMID 34540840, 2021).
inflammatory bowel disease (11 papers, 2020 to 2026). A spectrum of small and large bowel inflammatory diseases of unknown etiology. "In this comprehensive review, we explore the various cGAS signaling pathways, the role of cGAS dysregulation in inflammatory bowel disease (IBD) and GI malignancies, and the therapeutic interventions targeting these pathways." (PMID 39050748, 2024). "The importance of cGAS activation in the development and progression of inflammatory bowel disease and gastrointestinal cancers has been and continues to be explored." (PMID 39050748, 2024). "Although SENP7 has been reported to potentiate cGAS activation and contribute to the expansion of proinflammatory γδT cells in inflammatory bowel disease, the related studies used an in vivo model of SENP7 knockdown." (PMID 35143421, 2022). "This review summarizes the most recent developments on the function of the cGAS-STING regulatory pathway in colorectal tumors and inflammatory bowel disease." (PMID 41624832, 2026). "For example, mutations in gene ATG16L1 promote the production of IL-22 in the intestinal epithelium through cGAS/STING pathway, which result in excessive epithelial cell death and inflammatory bowel disease (IBD)." (PMID 35006429, 2020). "Some reports have suggested cGAS/STING modulation as a potential treatment of ulcerative colitis and inflammatory bowel disease (IBD)." (PMID 35406723, 2022).
non-alcoholic steatohepatitis (11 papers, 2021 to 2025). "The sixth ailment associated with the cGAS–STING pathway is nonalcoholic steatohepatitis (NASH)." (PMID 37686127, 2023). "In addition, abnormal activation of cGAS–STING induced non-alcoholic steatohepatitis (NASH) in the context of mitochondrial dysfunction." (PMID 35536585, 2022). "Oxidative stress and apoptosis cause mitochondrial DNA leaking in nonalcoholic fatty liver disease (NAFLD), nonalcoholic steatohepatitis (NASH), alcoholic liver disease (ALD), and renal diseases; this “foreign” DNA is detected by cGAS-STING signaling and subsequently triggers the immune system." (PMID 39114669, 2024). "Could we treat both diseases by inhibiting the activation of the cGAS-STING pathway, especially in patients with psoriatic relapses with or without the conversion of steatohepatitis to nonalcoholic steatohepatitis?" (PMID 38917217, 2024).
renal fibrosis (11 papers, 2022 to 2026). A final common manifestation of a wide variety of chronic kidney diseases characterized by glomerulosclerosis and tubulointerstitial fibrosis. "To identify the underlying mechanisms of renal fibrosis in heat-stressed hens, we measured the expression of cGAS-STING pathway-related genes by qRT-PCR." (PMID 37268977, 2023). "Emerging evidence indicates the cyclic GMP-AMP synthase-stimulator of interferon genes (cGAS-STING) signaling pathway has exerted a crucial influence on the progression of renal fibrosis." (PMID 42099585, 2026). "By synthesizing recent advances in cGAS-STING-mediated macrophage reprogramming for renal fibrosis intervention, this review aims to provide a foundation for precise therapeutic development." (PMID 42099585, 2026). "The loss of SQOR then induces mitochondrial damage and mtDNA release, activates the cGAS–STING innate immune pathway, and causes glycolytic reprogramming and excessive extracellular matrix deposition, thereby promoting renal fibrosis." (PMID 41210256, 2025). "Recent studies demonstrated that activation of cGAS-STING signaling pathway contributed to folic acid or hypoxia-induced renal fibrosis." (PMID 38972937, 2024). "Collectively, these data indicate that VDAC1 oligomerization is involved in mtDNA release and activation of cGAS-STING signaling pathway in the progression of renal fibrosis." (PMID 38972937, 2024). "In this study, the expression of VDAC1 was elevated in kidney after UUO, and blockage of VDAC1 attenuated UUO-induced renal fibrosis, inflammation and cGAS-STING pathway activation." (PMID 38972937, 2024). "Deletion of STING attenuated symptoms of renal fibrosis, indicating the critical role of cGAS/STING in the pathology of renal fibrosis." (PMID 37354378, 2023). "This review delineates the regulatory role of the cGAS-STING signaling pathway in macrophage-related renal fibrosis and critically evaluates emerging innovative strategies targeting this pathway, including small molecule inhibitors, nanocarrier-based delivery systems, and gene editing technologies." (PMID 42099585, 2026). "This study also suggests that, in addition to Beclin-1, signaling molecules in pathways of ISR and cGAS-STING may become promising therapeutic targets for renal fibrosis." (PMID 36875088, 2023). "Mechanistically, deficiency of PC reduces sulfide:quinone oxidoreductase (SQOR) stability and accelerates mitochondrial damage, promoting mtDNA leakage and cGAS‐STING signaling activation, which in turn, leads to glycolysis increase and renal fibrosis." (PMID 39836535, 2025). "In our study, we found that PC knockout in mice increased mtDNA leakage, significantly activated the cGAS‐STING pathway, and subsequently upregulated the expression of glycolytic enzymes such as HK2 and PKM2, promoting renal fibrosis." (PMID 39836535, 2025). "This leads to mitochondrial morphological and functional disruption, increased mtDNA release, activation of the cGAS‐STING pathway, and elevated glycolysis levels, and ultimately, promotes renal fibrosis." (PMID 39836535, 2025). "Mechanistically, PKC-δ activation resulted in mitochondrial membrane VDAC1 oligomerization, followed by the release of mtDNA, and subsequently activated cGAS-STING signaling pathway, and promoted inflammatory responses which contributed to the renal fibrosis." (PMID 38972937, 2024). "And the gene expression of cGAS and STING were positively related to renal fibrosis in CKD patients." (PMID 35680856, 2022). "This cGAS‐STING‐PERK pathway regulates cap‐dependent messenger RNA translation, innate immune control of cellular senescence or organ fibrosis, and non‐canonical targeting or drug treatment of the cGAS‐STING pathway gene can alleviate pulmonary and renal fibrosis." (PMID 38459658, 2024).
renal fibrosis (continued). "Thus, we speculate that the PC pathway may regulate the activation of the cGAS‐STING signaling pathway, and the upregulation of glycolysis may be the downstream mechanism of PC/SQOR/STING‐mediated renal fibrosis." (PMID 39836535, 2025).